ALB (albumin)
Diseases named in the same sentence as ALB in open-access papers (continued):
Sharing a sentence is not in itself a finding about the gene and the disease.
hip fracture (continued). "In numerous studies, low serum albumin levels have been found to negatively correlate with hip fracture mortality." (PMID 37701840, 2023). "The reduced serum albumin is common in elderly patients with hip fracture, and in this study 64.5% of patients had albumin less than 35 g/L." (PMID 33213498, 2020). "Among routine laboratory blood tests that we assessed as secondary outcome, low Hb, albumin, and TLC, and high creatinine, potassium, troponin T, and CRP have all been reported be associated with poor outcome in hip fracture patients." (PMID 32466360, 2020). "We undertook a retrospective analysis of one-year postoperative mortality of our hip fracture patients and established their admission serum albumin levels to see if there was any correlation between this and one-year mortality." (PMID 23317722, 2013). "In addition, the prognostic nutritional index (PNI), derived from albumin concentration and lymphocyte count, has been shown to independently predict unfavorable survival outcomes in hip fracture patients at 2 years of follow-up." (PMID 40041469, 2025). "Furthermore, this paper constitutes a unique attempt to compare diabetic and nondiabetic elderly patients with hip fractures regarding VD, PTH, hip fracture severity, serum ALB, and BMD." (PMID 40313432, 2025). "Given the clear associations between hemoglobin, lymphocyte, platelet, albumin and survival, we hypothesized that the HALP score may serve as an independent prognostic indicator for mortality following hip fracture." (PMID 40041469, 2025). "The authors reported that sarcopenic hip fracture patients had significantly lower serum albumin, IGF-I, insulin-like growth factor binding protein 3 (IGFBP-3), and free testosterone levels, as well as impaired beta cell function according to homeostasis model assessment (HOMA beta)." (PMID 39769198, 2024). "Therefore, time from injury to admission, smoking history, serum-albumin levels, and D-dimer levels were independent risk factors for preoperative CMVT in geriatric hip fracture patients." (PMID 37720507, 2023). "Albumin has been shown to predict in-hospital mortality and one-year mortality after hip fracture." (PMID 34765379, 2021). "We measured lower DBP and albumin levels in patients with hip fracture than in control persons." (PMID 30071650, 2018). "We performed a backward stepwise multiple linear regression with change in serum albumin, measured from baseline to 40 days, as dependent variable and age, hip fracture, baseline MUAC and total length of hospital stay (within study period) as independent variables." (PMID 21663680, 2011). "These factors may coexist in elderly hip fracture patients, affecting their albumin levels." (PMID 38528491, 2024). "However, serum albumin concentration rapidly declined when a hip fracture occurred." (PMID 37620804, 2023). "The generalized estimating equation analysis indicated that the length of postoperative follow-up time, serum albumin level, patient cognitive status, and handgrip strength were considerably associated with QoL and ADL recovery prognosis in the Taiwanese older adults following hip fracture." (PMID 35055417, 2022). "Consequently, the serum albumin concentration is already in a state of change in acute trauma patients due to accompanying endothelial damage, so it may be difficult to establish baseline values in hip fracture patients." (PMID 38792928, 2024). "This study aims to evaluate biomarkers, especially the glucose-albumin ratio (GAR), for predicting POP in elderly hip fracture patients." (PMID 39496632, 2024). "We found a linear dose–response relationship between serum albumin levels and POD in hip fracture patients: the lower the albumin level, the higher the incidence of POD." (PMID 38420358, 2024).
hip fracture (continued). "The aim of this study is to investigate the potential effects of admission and postoperative levels of RDW, albumin, and RDW/albumin (RA) ratio on predicting 1-year mortality following hip fracture surgery in elderly patients." (PMID 37701840, 2023). "In relation to serum albumin levels of ≥35 g·L−1, a higher prevalence was demonstrated among patients in the non-recurrent hip fracture group compared to the recurrent hip fracture group (32.4% vs. 17.3%, p= 0.010)." (PMID 41294891, 2025). "Although this has been demonstrated in the spine and elective arthroplasty settings, there is a paucity of evidence with regard to the effect of low serum albumin on rates of SSI following surgery for adult patients suffering from traumatic and acute hip fractures." (PMID 38817798, 2024). "Notably, the hip fracture patients in the highest plasma BNP tertile were older and scored lower in the handgrip strength test, cognitive FIM, hemoglobin, serum albumin, and GNRI than patients in the first tertile." (PMID 32790735, 2020). "In prior publications, laboratory evaluation results, including admission hemoglobin concentration, blood level of albumin, and Neutrophil to lymphocyte ratio (NLR), were found to be significantly related to 30-day or 1-year mortality in patients with a hip fracture." (PMID 32599880, 2020). "Significantly lower concentrations of all 25OHD fractions and binding proteins (DBP, albumin) as well as Ca, but not albumin corrected Ca, were observed in patients with hip fracture as compared to the control group." (PMID 30071650, 2018). "This may explain why nonsurvivors of hip fracture in our meta-analysis simultaneously presented with a lower albumin level and higher CRP level." (PMID 36894998, 2023).
peripheral vascular disease (67 papers, 2009 to 2026). Any disorder affecting blood flow through the veins or arteries outside of the heart. "The lower value of IgM and albumin globulin ratio in this group of patients corresponds with literature data as a marker of an increased risk of vascular disorders, including ischemic foci of the brain." (PMID 40806171, 2025). "As oxidative stress is associated with both increased cardiovascular and peripheral vascular disease, we measured ischaemia modified albumin and calculated the IMAR to allow comparison between patients." (PMID 34614018, 2021). "Cardiovascular disease (CVD) is a constellation of heart, brain, and peripheral vascular diseases with common soil hypothesis of etiology, and its subtypes have been well-established in terms of the albumin-mortality association." (PMID 36523355, 2022). "Previous studies noted that pathological vascular disorders may cause leakage of large molecules such as albumin, exacerbating changes in the choroidal thickness in the LCVL." (PMID 32915894, 2020). "GCS, SPO2, albumin, AST/ALT, glucose, potassium, PTT, and peripheral vascular disease were the independent risk factors according to the multivariate analysis results." (PMID 37599814, 2023). "Albumin is a strong indicator for patients who died of gastrointestinal disease and peripheral vascular disease." (PMID 38106617, 2023). "Those who refused were more likely to have peripheral vascular disease (p = 0.001), low albumin (p = 0.0187), low sodium (p = 0.0422), and ineligible for kidney transplant (p = 0.005)." (PMID 38093284, 2023). "The effect of TCBN treatment on retinal vascular permeability in OIR-induced vasculopathy was determined by analysis of fluorescein leakage using FA and albumin extravasation using Western blotting of retinal lysates." (PMID 37080089, 2023). "However, cardiovascular disease is a constellation of heart, brain, and peripheral vascular diseases with common soil hypothesis of etiology, and the association between albumin and mortality in CVD as a whole remains poorly understood, especially the non-linear association." (PMID 36523355, 2022). "For example, when bedridden CKD patients with hemiplegia and peripheral vascular disease exhibit a low level of serum albumin and a high level of calcium, predicted 1-year mortality is >25% according to our risk score." (PMID 26057129, 2015). "In univariate Cox regression, patient's age, the presence of peripheral vascular disease, serum albumin, and C-reactive protein and creatinine clearance were independent predictors of all-cause mortality." (PMID 24959538, 2013). "The risk markers with the largest variability across outcomes were discontinued status (i.e., withdrawal from hemodialysis), number of sessions in the previous month, claim for atherosclerotic heart disease, claim for peripheral vascular disease, and serum albumin level." (PMID 39680439, 2025). "Another study from China tested several risk factors for DVT after hip fracture surgery: Only six demonstrated an independent effect on DVT occurrence, including history of a VTE event, time from injury to DVT screening, BMI, peripheral vascular disease, reduced albumin, and D-Dimer > 1.0 mg/L." (PMID 39941396, 2025). "Although increasing HbA1c was associated with a higher incidence of peripheral vascular disease, this association was no longer significant after correction for urinary albumin, creatinine, and anti-diabetic medication." (PMID 31774849, 2019). "The variables included in the nomogram were GCS, SPO2, albumin, AST/ALT, glucose, potassium, PTT, and peripheral vascular disease." (PMID 37599814, 2023).
acute respiratory distress syndrome (66 papers, 2012 to 2026). Progressive and life-threatening pulmonary distress in the absence of an underlying pulmonary condition, usually following major trauma or surgery. "Researchers have reported that the lactate–albumin ratio (LAR) serves as a reliable predictor of risk in acute respiratory distress syndrome patients and is positively correlated with 28-day mortality in ARDS patients." (PMID 40351465, 2025). "Among the AKI patients, acute respiratory distress syndrome and low serum albumin on admission were considered independent risk factors for stage 3 AKI (both p < 0.05)." (PMID 32503180, 2020). "Our study demonstrated that preoperative RDW/albumin was a risk factor for surgical outcomes such as prolonged hospital stay, 5-year, and overall mortality, which is in line with a previous study on patients with acute respiratory distress syndrome." (PMID 36399446, 2022). "A randomized controlled study has shown that ALB level works as an independent risk factor for acute respiratory distress syndrome (ARDS) in patients with severe infection." (PMID 40438354, 2025). "This retrospective study comprehensively investigated the prognostic significance of the albumin-corrected anion gap (ACAG) in patients with acute respiratory distress syndrome (ARDS), and its association with 28-day all-cause mortality." (PMID 41264595, 2025). "The serum albumin level has been verified inversely associated with development of acute respiratory distress syndrome (ARDS) in COVID‐19 patients." (PMID 32914892, 2020). "Increases in total phospholipases A2 activity, total protein, albumin, plasminogen activator inhibitor-1, soluble receptor for advanced glycation end products, and platelet activating factor-acetyl choline were most strongly associated with acute respiratory distress syndrome diagnosis." (PMID 30755248, 2019). "Our findings indicate that protein and albumin levels in bronchoalveolar lavage (BAL) fluid are elevated in severe acute respiratory distress syndrome (ARDS) cases." (PMID 40017475, 2025). "In a very recent work by Wang HX and colleagues, the lactate/ albumin ratio was an independent predictive factor for 28-day overall mortality in patients with acute respiratory distress syndrome (ARDS)." (PMID 39685564, 2024). "Recently, it has been reported that the ratio of RDW/albumin ratio, which is the combined index of RDW and albumin, is associated with 60-day mortality in patients with acute respiratory distress syndrome." (PMID 36399446, 2022). "Decreased serum albumin is reported as a poor prognostic factor for PJP, and as a risk factor for acute lung injury/acute respiratory distress syndrome." (PMID 36552932, 2022). "In the studies conducted, the serum albumin level and acute respiratory distress syndrome (ARDS) development in patients show an inverse proportion." (PMID 34784756, 2021). "Albumin level has been identified in adults as an evaluation index of acute respiratory distress syndrome, but there have been few studies in neonates." (PMID 34485188, 2021). "However, they did observe a significant reduction in acute respiratory distress syndrome within the albumin group (3.5% vs 13.7%, p = 0.008)." (PMID 40678365, 2025). "“Acute respiratory distress syndrome,” “Albumin ratio,” “Arterial blood pressure,” “External validation,” “To-albumin ratio,” “Retrospective study,” “Bayesian filter,” “Patient profiles,” “Treatment-related complications,” and “Prediction” are potential main topics in this field." (PMID 36187634, 2022). "Although the circulating level of albumin is not expected to serve as the nutrition marker for a patient’s inflammatory response, a recent study claimed that the low albumin level could evolve into acute respiratory distress syndrome." (PMID 35415243, 2022). "It is already shown that the administration of albumin in critically ill patients with acute respiratory distress syndrome might have its advantages." (PMID 33968298, 2021).
acute respiratory distress syndrome (continued). "Albumin may improve oxygenation in patients with acute respiratory distress syndrome by reduced alveolar-capillary permeability, decreased inflammatory cell infiltration, enhanced total plasma antioxidant capacity, and faster hemodynamic stabilization." (PMID 29147647, 2017). "Notably, colloid therapy with serum albumin could improve oxygenation in patients with acute respiratory distress syndrome." (PMID 34122505, 2021). "Accordingly, increased OLA and decreased albumin plasma levels seem to predict the development of acute respiratory distress syndrome (ARDS)." (PMID 22529526, 2012). "In acute respiratory distress syndrome (ARDS), LAR correlates positively with 28-day mortality, exceeding predictions based on lactate or albumin alone and comparable to the SPASII score." (PMID 40687397, 2025). "In patients with Acute Respiratory Distress Syndrome (ARDS), we can determine the severity of the condition by looking at protein and albumin levels in the BAL fluid." (PMID 40017475, 2025). "However, the mean protein ELF-to-plasma ratio in adults varies from 0.13 in healthy volunteers to 0.25 in patients with severe acute respiratory distress syndrome (ARDS) for total protein, versus 0.1 in healthy volunteers to 0.19 in ARDS for albumin." (PMID 38036299, 2024). "Moreover, additional predictors of mortality at admission to an intensive care unit (ICU) have been identified as acute respiratory distress syndrome (ARDS), interleukin (IL)-6, serum albumin, and D-dimer levels, as well as chest CT severity score." (PMID 35208631, 2022). "Based on the literature review we studied the commonly reported risk factors such as hypertension, diabetes, chronic obstructive pulmonary disease, dyspnoea, history of substance use, gender, acute respiratory distress syndrome (ARDS), history of smoking, older age, albumin, and D-dimer." (PMID 34418980, 2021). "A reduction in serum albumin levels (below 35 g/L), combined with elevated protein levels in bronchoalveolar lavage (BAL), serves as a predictor of poor outcomes in patients with acute respiratory distress syndrome (ARDS), as indicated by a p-value of less than 0.01 (ANOVA)." (PMID 40017475, 2025). "We studied the value of routine biochemical variables albumin, C-reactive protein (CRP) and lactate dehydrogenase (LDH) to improve prediction and monitoring of acute respiratory distress syndrome (ARDS) severity in the intensive care unit." (PMID 25888398, 2015). "In acute respiratory distress syndrome (ARDS), albumin improves oxygenation in hypoalbuminemic patients, without survival benefits." (PMID 41827398, 2026). "Ampion is the filtrate of human serum albumin (low molecular weight), which has the potential to reduce inflammatory cytokines correlated with COVID-19 disease and respiratory complications, such as acute lung injury (ALI) and acute respiratory distress syndrome (ARDS)." (PMID 34371768, 2021).